DPY19L2 (dpy-19 like 2)
Description:
Probable C-mannosyltransferase that mediates C-mannosylation of tryptophan residues on target proteins. Required during spermatogenesis for sperm head elongation and acrosome formation. Also plays a role in acrosome attachment to the nuclear envelope (By similarity).
Synonyms: FLJ32949; SPATA34; SPGF9
Tractability: Antibody: UniProt predicts a signal peptide or a membrane-spanning region.
Gene: Protein-coding gene on chromosome 12 (63,558,913 to 63,668,939, reverse strand). Ensembl gene ENSG00000177990.
Subcellular location: Nucleus inner membrane
Subcellular location (Human Protein Atlas): Mitochondria; Nucleoplasm
Gene Ontology:
Molecular function: mannosyltransferase activity
Biological process: spermatid development
Cellular component: nucleus; nuclear inner membrane; membrane
Genetic constraint (gnomAD): Loss-of-function variants: 26 observed, 49.26 expected, observed/expected ratio (o/e) 0.53, 90% interval 0.39 to 0.73. The upper end of that interval is the gene's LOEUF score, 0.73, which puts it in group 3 of 6, group 1 being the genes least tolerant of losing a copy. Missense variants: 492 observed, 630.36 expected, observed/expected ratio (o/e) 0.78, 90% interval 0.72 to 0.84. Synonymous variants: 195 observed, 221.31 expected, observed/expected ratio (o/e) 0.88, 90% interval 0.78 to 0.99.
Gene-disease validity (ClinGen):
ClinGen rates the evidence that DPY19L2 causes each of these diseases.
male infertility due to globozoospermia (autosomal recessive): Definitive. A male infertility due to sperm disorder characterized by the presence, in sperm, of a large majority of round-headed spermatozoa that lack the acrosome and have an aberrant nuclear membrane and midpiece defects.
Homologues: Orthologues: chimpanzee DPY19L2 (99% identical), rabbit DPY19L2 (83% identical), pig DPY19L2 (82% identical), dog DPY19L2 (81% identical), mouse Dpy19l2 (79% identical), rat Dpy19l2 (77% identical), guinea pig DPY19L2 (58% identical). Paralogues in human: DPY19L1 (60% identical), DPY19L3 (26% identical), DPY19L4 (23% identical).